IDO1 (indoleamine 2,3-dioxygenase 1)
Diseases named in the same sentence as IDO1 in open-access papers (continued):
Sharing a sentence is not in itself a finding about the gene and the disease.
tumor (continued). "IFN-γ is mainly produced by tumor-infiltrating lymphocytes, which may lead to the upregulation of IDO-1 through a negative feedback mechanism." (PMID 39062529, 2024). "At the same time, loss of NF1, TSC1, or TβRII promoted the production of soluble inflammatory mediators such as IL6 and IDO1, which resulted in a non-cell-autonomous immune-suppressive tumor microenvironment that is characterized by increased LAG3+ CD8 and CD4 T cells." (PMID 38997291, 2024). "The AKR1C3+ cells could catalyze the paclitaxel to the non-toxic hydroxyl metabolites, accompanied with activated ROS and inflammation; the IDO1+ cells may inhibit T cell function by consuming tyrosine and HEY1+ cells enhanced the cell proliferation to promote tumor survival." (PMID 38227591, 2024). "Thus, despite accumulating in the colon they are not sufficient to induce an anti-tumour microenvironment, rather via induction of IDO1 expression, promote one that supports tumour development." (PMID 39242821, 2024). "Despite the abundant in vitro evidence indicating a tumor-promoting role for IDO1, elucidation of the effects exerted by IDO1 in vivo have been complicated by the expression of IDO1 in both tumor cells and non-malignant host cells of cancer patients, of which contributions vary among cancer types." (PMID 39211039, 2024). "A clinical trial of the IDO1 inhibitor epacadostat in the treatment of melanoma, however, with or without pembrolizumab, an inhibitor of Programmed Death-1 (PD-1), failed to produce a significant reduction of tumour development." (PMID 39201726, 2024). "Alternatively, this poor performance may indicate that IDO1 activity is not required to fuel tumour growth in established cancers." (PMID 39242821, 2024). "Tumor growth and progression were reduced by increased effector T cell invasion when COX-2 expression was prevented, resulting in a parallel reduction in PD-L1 and IDO1 levels in the tumor microenvironment, which were jointly responsible for the tumor survival." (PMID 37296860, 2023). "Therefore, we believe treatment targeting IDO1 or directly, these miRNAs, could regulate the gene expressions in surrounding cells, shaping TME against tumor progression." (PMID 37284323, 2023). "Whereas IDO1 has largely been studied in the context of Trp-IDO1-Kyn-AhR signaling, IDO1 may also promote tumor progression through non-enzymatic functions." (PMID 37876966, 2023). "The expression of four TME-related genes (CXCL10, LZTS2, IDO1, and MAB21L2) that predict the TME signature of CRC was validated in four GEO datasets: GSE20916 (145 samples), GSE21815 (141 samples), GSE3629 (121 samples), and GSE89287 (71 samples), which contained normal control and tumor samples." (PMID 37596528, 2023). "Recent studies showed that IDO1-dependent tryptophan metabolism is a bona fide one-carbon source for folate-dependent nucleotide synthesis because TRP can be substituted for serine as a one-carbon donor, with serine deprivation improving the anti-tumor activity of IDOi." (PMID 37226257, 2023). "Together, these results yielded a conceptual model whereby IDO1 acts as a regulatory node at the interface between IFNγ and IL6, shifting the inflammatory microenvironment to a tumor-promoting state by preventing the ability of IFNγ to pare back the tumor neovasculature." (PMID 37182174, 2023). "To test the tumorigenicity of KPIC Ido-1 KO cells, we subcutaneously transplanted KPIC Ido-1 KO organoids into immunocompetent C57BL/6 mice (n = 7), and found that KPIC Ido-1 KO organoids did not form a subcutaneous tumor in C57BL/6 mice within 25 d after transplantation." (PMID 36517670, 2023). "Tumor cells and recruited immunosuppressive cells release cytokines such as interleukin (IL)-10, transforming growth factor–beta (TGF-β), IL-4, and the enzyme indoleamine 2,3-dioxygenase 1 (IDO-1) that contribute a cytokine milieu that further suppresses infiltrated immune cells." (PMID 36167831, 2023).
tumor (continued). "In this case, rather than being acquired under selective pressure, IDO1 induction precedes tumor initiation, priming the inflammatory TME to enable nascent tumors to bypass the elimination and equilibrium phases of immune surveillance and proceed directly to the escape phase." (PMID 37182174, 2023). "Similar to NK cells, the activity of both IDO1 and COX-2 leads to a decrease in the expression of the activating receptor NKG2D on the surface of iNKT cells, as well as a reduction in the levels of intracellular granzyme and perforin, which are essential for recognizing and eliminating tumor cells." (PMID 37444608, 2023). "TDO2 expression in CR cells was very low to non-detectable when compared to IDO1 expression, leading to the idea that IDO1 may be more significant for metabolism in these tumor types." (PMID 37226257, 2023). "Moreover, emerging data suggests that KP-related enzymes, such as IDO1, can promote tumor progression through functions that are independent of enzymatic activity." (PMID 37876966, 2023). "They found that nonenzymatic tumor cell IDO1 activity increased expression of complement factor H (CFH) and its isoform, factor H like protein (FHL-1) in human GBM, resulting in increased intratumoral Tregs and myeloid-derived suppressor cells, accelerated tumor growth and poor survival." (PMID 37876966, 2023). "IDO1 was reported to be upregulated in the tumour cells but not significantly in immune cells." (PMID 37041200, 2023). "Furthermore, a phase I clinical trial showed that the combination of the IDO-1 inhibitor navoximod (GDC-0919) with atezolizumab (PD-L1 inhibitor) is characterized by good tolerability and acceptable anti-tumour activity in patients with solid tumours, including one patient with HNSCC." (PMID 36980527, 2023). "Interferon-γ induces CD8+ T cells to antigen (Ag)-specific CTLs and CD4+ T cell differentiation, however, continuous exposure to interferon-γ may induce T cell exhaustion and tumor progression by inducing immune escape mediators, including PD-L1, STAT3, and IDO1." (PMID 36006412, 2022). "Therefore, we first aimed to mimic an IDO1-dependent TME where we could assess how tumor and CD8+ T cells interacted when TRP metabolism was manipulated through IDO1 expression." (PMID 35245456, 2022). "As immunosuppressive molecules (e.g., PD‐L1, IDO1, and IL‐18BP) that can be induced by interferon‐gamma (IFN‐γ) are generally important to facilitate immune evasion by tumor cells, we wondered whether the expression of these immunosuppressive molecules in NPC cells is affected by CBX1." (PMID 36310139, 2022). "Accordingly, the CRISPR/Cas9 nanosystem developed in this research can efficiently enrich the tumor region under probiotic drive and can precisely and controllably knock down IDO1 under US irradiation, avoiding the lack of targeting and drug resistance of traditional inhibitors." (PMID 36550159, 2022). "For example, Ido1 expression relative to tumor size shows a significant negative correlation." (PMID 35775614, 2022). "Using mRNA from diffuse and intestinal GC tumor samples of a Western cohort, this study reports the expression level of the immunomodulatory aryl-hydrocarbon receptor (AhR), and genes involved in immune suppression (PD1, PD-L1, PD-L2) and the early steps of tryptophan metabolism (IDO1, IDO2, TDO2)." (PMID 35203450, 2022). "Secondly, we did not test the IDO1 protein in tumor tissues of NSCLC patients in this research." (PMID 35872931, 2022). "The adaptive response is triggered by tumor-specific T cells via the production of IFN-γ and tumor-infiltrating lymphocytes (TILs), which can induce immune checkpoint molecules (such as CTLA-4) or immunosuppressive mediators (such as IDO1) to exert immunosuppressive effects." (PMID 35296094, 2022). "In addition to the role of IDO1 in immunosuppression, more researchers are currently paying attention to the role and mechanism of IDO1 independent of immune tolerance in promoting tumor development." (PMID 35760783, 2022).
tumor (continued). "However, β-lapachone is also a potent IDO1 inhibitor with an IC50 of around 97 nM, and thus β-lapachone is also likely to alter the tumor immune environment, contributing to the clearance of tumor cells." (PMID 36408235, 2022). "Similarly, in our result, the relationship between IDO1 and PFS was different from OS and DFS, which may be explained by the included tumor types." (PMID 36212460, 2022). "Correspondingly, when IDO1 was highly activated in MDSCs, the increased infiltration of CD4 + CD25 + FoxP3 + Tregs and the enhancement of immunosuppressive function could be observed in the tumor." (PMID 35681736, 2022). "Therefore, here, a self-driven multifunctional delivery vector is constructed to efficiently deliver the CRISPR-Cas9 nanosystem for indoleamine 2,3-dioxygenase-1 (IDO1) knockdown in order to amplify immunogenic cell death (ICD) and then reverse tumor immunosuppression." (PMID 36550159, 2022). "Notably, while IDO1 is overexpressed in gliomas, the kynurenine/tryptophan ratio is not predictive of disease progression in that tumor model, suggesting that the biological significance of this ratio is not universal." (PMID 35681770, 2022). "EC tumor cells can also escape from immune surveillance by inducing DC-triggered TIL apoptosis under the influence of RCAS1, or by promoting the DC transformation into an immunosuppressive phenotype, with PD-L1 and SIRPα expression and IDO1 production, inhibiting CD8+ T cell activity." (PMID 33995371, 2021). "Furthermore, in the phase III trial (ECHO-301/KEYNOTE-252), the high proportion of IDO1-positive samples was mainly attributable to the staining of immune cells rather than tumor cells." (PMID 33557876, 2021). "IDO1 is not normally expressed under physiological conditions in human cells, but it is expressed in subsets of antigen-presenting cells (APCs), endothelial, and tumor cells." (PMID 34944437, 2021). "IDO1 deficient mice also exhibited diminished CD8+ TIL frequency, but the complete absence of IDO1 expression in tumor and host significantly increased CD8+ TIL frequency on Day 57, indicating that both host- and tumor-derived IDO1 contribute to reduced TIL accumulation in the ovarian TME." (PMID 34025677, 2021). "IDO1 inhibitors may enhance the efficacy of anti-PD-1/PD-L1 drugs, potentiating the action of immune effectors, without directly killing tumor cells or initiating a de novo anti-tumor immune response." (PMID 34830179, 2021). "Also, ID8 by its nature is not a typically inflammatory tumor model, however, we show in these studies that the TILs that enter the tumor can be modulated by IDO1 and has an impact on efficacy." (PMID 34025677, 2021). "Although TDO and IDO2 are not the current focus of this article, researchers should pay close attention to them as targeting tumour dormancy via the Kyn/AhR signalling may not always be IDO1 specific." (PMID 34539663, 2021). "Moreover, whilst a large body of literature had focused on eliminating active cancers through IDO1 inhibition, investigation on the relation between IDO1 and tumour dormancy is lacking." (PMID 34539663, 2021). "Indeed, several studies concerning the IDO1/Kyn/AhR metabolic axis argue that IFN-γ is needed only for initiation but not maintenance of tumour dormancy – some other factors have been involved in the consecutive IDO1 activity." (PMID 34539663, 2021). "Neither PD-1, IDO1, nor B7-H4 expression showed general or tumor type-specific prognostic value." (PMID 34799669, 2021). "Because tumor cells can upregulate multiple immune checkpoint pathways to evade the immune response, therefore, selective inhibition of IDO1 may not be sufficient to promote tumor regression in most patients." (PMID 34201791, 2021). "Therefore, increased IDO1 activity facilitates immunosuppression by metabolizing tryptophan and results in deceased effector T cell proliferation and promotes Treg differentiation, and CCL2 recruits MDSCs to the tumor more efficiently." (PMID 35126382, 2021).
tumor (continued). "IDO1 was overexpressed in tumours from never‐smokers and never‐drinkers; and gene expression profiles showed that IDO1 together with PD‐L1 were co‐overexpressed in HNSCCs40, 41, 42 compared to IDO1 presence in normal head and neck tissue." (PMID 34053179, 2021). "A role as inhibitor of NK effector functions has been recently described also for IDO1, a rate-limiting metabolic enzyme that converts tryptophan into downstream catabolites kynurenines (KYN) and is involved in the establishment and maintenance of peripheral tolerance and tumor immune escape." (PMID 34975867, 2021). "This aspect clearly has negative implications for ICI therapy, since increased IDO1 activity may increase tumor-infiltrating Treg cells, decrease TILs and accelerate tumor growth." (PMID 33467713, 2021). "The IDO1 gene is primarily expressed by myeloid cells and stroma in response to inflammatory immune signals (although it can be expressed by tumor cells), whereas IDO2 and TDO are largely unresponsive to immune stimuli and have a broader expression pattern; thus, this discussion will focus on IDO1." (PMID 34456909, 2021). "However, analytical approaches of IDO1 determination, i.e., the used in this study HPLC-DAD might better reflect the status of IDO1 enzyme in the tumor and should be considered in final tissue assessment." (PMID 33922995, 2021). "Programmed death-ligand 1 (PD-L1) and indoleamine 2,3-dioxygenase 1 (IDO1) expression and signal-regulatory protein alpha (SIRPα), forkhead box P3 (FOXP3), and cluster of differentiation 8 (CD8) infiltration were assessed by immunohistochemical studies of 137 tumor tissues from 96 patients." (PMID 34285260, 2021). "However, although small-molecule IDO1 inhibitors that showed promise in early-stage tumor immunotherapy clinical trials, were not effective in a phase III trial." (PMID 33924971, 2021). "TCC-Sup did not express IDO-1, suggesting that the tumor-mediated effects on ILCPs might not depend on kynurenines." (PMID 33554861, 2021). "Finally, we demonstrate that combined blockade of signalling ligands PD-L1 and TGFβ1 together with inhibition of indoleamine 2,3-dioxygenase 1 (IDO1) was able to reverse, in part, the suppressive effects of peritumoral CD90+CD73+ cells on tumor-infiltrating lymphocytes (TILs)." (PMID 34740105, 2021). "The cellular pharmacodynamic effects of IDO1 activity include the inhibition of antigen-specific CD8+ T cell proliferation, stimulation of differentiation of naïve CD4+ T cells to FoxP3+ regulatory T cells (Tregs), the activation of Tregs, and the recruitment of MDSC to the tumor." (PMID 32637034, 2020). "IDO1 blockade using GDC-0919 did not confer significant benefit either alone or in combination with anti-PDL1—even if a trend of optimization was observed with a tumor rejection observed on 3 out of 15 mice tested." (PMID 32194552, 2020). "Nonetheless, the use of small-molecule compounds to modulate IDO1/2, TDO2, and AhR in glioma and meningioma cell lines has already proven that in contrast to enzyme inhibition, AhR antagonists markedly reduce tumor cell viability, i.e., AhR may be a therapeutic target in these types of cancer." (PMID 32325928, 2020). "Irrespective of the specific functions of IDO1 in the tumor microenvironment, we did not observe any modulation of IDO1 activity by Tα1, suggesting that Tα1 may activate IDO1 in conditions of overactivated immune response." (PMID 32817121, 2020). "Indeed, we did not observe increased levels of kynurenines or IDO1 expression at the tumor site upon Tα1 treatment." (PMID 32817121, 2020). "However, the studies on changes of tumor IDO1 expression after neoadjuvant therapy are lacked in ESCC." (PMID 32733806, 2020). "The higher level of IDO1 could result in the lack of tryptophan in tumor microenvironment, which directly reduces the proliferation ability and functions of immune cells." (PMID 31315643, 2019).
tumor (continued). "Moreover, a preclinical study found that IDO1 had an independent influence on tumor cell’s resistance to radiation in the absence of immune cells, including effects on DNA repair and depletion of cells in G2/M of the cell cycle." (PMID 30717285, 2019). "Furthermore, a combination of IDO1 or AhR inhibitors to block this pathway and IFN-β treatment significantly decreased colony size and colony number of tumor cells, due to dormant tumor cells that were abrogated, which provided a novel and ideal treatment against cancer dormancy." (PMID 31297335, 2019). "Inhibitors of the IDO1-Kyn-AhR pathway could abolish the potential negative effects of CAI in the tumor microenvironment." (PMID 31511064, 2019). "Targeting IDO1 as a single agent therapeutic strategy failed to induce tumor regression." (PMID 31681327, 2019). "However, one study reported IDO-1 expression to be totally absent in tumor cells and only present in a few macrophages, while its expression was positively correlated with CD8+ T cell expression." (PMID 31192136, 2019). "To do this, we investigated the expression of IDO1 and medium-chain Acyl-CoA Dehydrogenase (ACADM) in primary and metastatic PCa by analyzing gene expression profiles from datasets containing androgen-ablation resistant PCa metastatic samples and normal and tumor adjacent tissues." (PMID 31842810, 2019). "IDO1 is not expressed in most tissues in adult humans under physiological conditions but is constitutively expressed in many types of cancer cells, stromal cells, and immune cells in the tumor microenvironment." (PMID 30068361, 2018). "Although we observed a tendency of tumors to be higher in IDO1-deficient animals, there was no statistical difference concerning the tumor growth kinetics up to 35 days, in both WT and IDO−/− not immunized mice, when tumors achieve a diameter of approximately 13-14 mm." (PMID 30186285, 2018). "Notably, expression of IDO1 in stromal cells and/or immune cells, but not in tumor cells, inhibited the antitumor effects of the gDE7, as demonstrated in IDO1-deficient mice." (PMID 30186285, 2018). "Comparing 0 and 10 day with day 14 post TC-1 transplantation, we observed a concomitant decrease in the number of IDO1-expressing DCs, macrophages, inflammatory monocytes and MDSCs in spleen and blood of TC1-grafted mice, which suggests that these cells are migrating to the tumor site." (PMID 30186285, 2018). "Thus, indoximod is rationalized to treat tumor cells overexpressing IDO1, IDO2 or TDO (or any combination thereof), which is not the case for an enzyme-selective inhibitor." (PMID 30254983, 2018). "Several key pathway molecules in the tryptophan pathway, including IDO-1, TDO-2, and kynurenine, participate in controlling immune tolerance and promoting tumor escape by regulating T cells and the proliferation, differentiation, and apoptosis of tumor cells via the AhR." (PMID 29487603, 2018). "Addition to the immunomodulatory effects of IDO1 on tumour cells, we speculated that IDC cells (via IFNγ) -induced IDO1 in ECs could catalyse the oxidation of L-tryptophan into kynurenine, which results in a reduction in the availability of tryptophan for the TSP1 synthesis by ECs." (PMID 29156701, 2017). "Interestingly, intracellular IDO1 expression in tumor cells displayed a regional rather than uniform expressing pattern, which often occurred in discrete geographic foci." (PMID 26895379, 2016). "Interestingly, co-culture with peripheral blood mononuclear cells (PBMC) significantly induced and maintained IDO1 expression in these tumor cells, predominantly through IFN-γ." (PMID 26895379, 2016).